OR51T1 (olfactory receptor family 51 subfamily T member 1)
Description:
Odorant receptor.
Synonyms: OR11-26
Tractability: Antibody: UniProt places it where antibodies can reach, with medium confidence; UniProt predicts a signal peptide or a membrane-spanning region; its Gene Ontology location is reachable by antibodies, with medium confidence.
Gene: Protein-coding gene on chromosome 11 (4,881,819 to 4,882,883, forward strand). Ensembl gene ENSG00000176900.
Subcellular location: Cell membrane
Pathways (Reactome):
Sensory Perception: Expression and translocation of olfactory receptors
Gene Ontology:
Molecular function: olfactory receptor activity; G protein-coupled receptor activity; signaling receptor activity
Biological process: cellular response to lipid; detection of chemical stimulus involved in sensory perception of smell; G protein-coupled receptor signaling pathway; system process
Cellular component: plasma membrane; membrane
Genetic constraint (gnomAD): Loss-of-function variants: 2 observed, 1.04 expected, observed/expected ratio (o/e) 1.92, 90% interval 0.51 to 1.94. That is too few expected variants to judge how well the gene tolerates losing a copy. Missense variants: 438 observed, 418.44 expected, observed/expected ratio (o/e) 1.05, 90% interval 0.97 to 1.13. Synonymous variants: 188 observed, 161.08 expected, observed/expected ratio (o/e) 1.17, 90% interval 1.04 to 1.32.
Homologues: Orthologues: chimpanzee OR51T1 (99% identical), rabbit OR51T1 (85% identical), dog OR51T1 (80% identical), rat Or51t1 (79% identical), mouse Or51t4 (78% identical), pig OR51T1 (74% identical). Paralogues in human: OR51F2 (48% identical), OR51C1 (48% identical), OR51G2 (47% identical), OR51G1 (45% identical), OR51L1 (45% identical), OR51A4 (45% identical), OR51Q1 (44% identical), OR51A2 (43% identical), OR51B5 (43% identical), OR51I2 (43% identical), OR51E1 (42% identical), OR51V1 (42% identical), and 39 more.